RNU6-471P (RNA, U6 small nuclear 471, pseudogene)
Gene: Small nuclear RNA gene on chromosome 6 (27,596,412 to 27,596,517, forward strand). Ensembl gene ENSG00000206671.
Homologues: Orthologues: chimpanzee U6 (99% identical), macaque U6 (93% identical). Paralogues in human: RNU6-166P (92% identical), RNU6-41P (92% identical), RNU6-15P (91% identical), RNU6-1122P (90% identical), RNU6-12P (90% identical), RNU6-13P (90% identical), RNU6-25P (90% identical), RNU6-31P (90% identical), RNU6-32P (90% identical), RNU6-44P (90% identical), RNU6-820P (90% identical), RNU6-1 (89% identical), and 1287 more.